RNU6-916P (RNA, U6 small nuclear 916, pseudogene)
Gene: Small nuclear RNA gene on chromosome 18 (6,936,912 to 6,937,020, reverse strand). Ensembl gene ENSG00000251897.
Homologues: Orthologues: chimpanzee U6 (90% identical), mouse Gm22352 (84% identical), rat U6 (83% identical), rabbit U6 (78% identical), dog U6 (76% identical). Paralogues in human: RNU6-41P (87% identical), RNU6-166P (86% identical), RNU6-12P (85% identical), RNU6-13P (85% identical), RNU6-15P (85% identical), RNU6-25P (85% identical), RNU6-29P (85% identical), RNU6-32P (85% identical), RNU6-44P (85% identical), RNU6-1 (84% identical), RNU6-1075P (84% identical), RNU6-116P (84% identical), and 1288 more.